MBP (myelin basic protein)
Diseases named in the same sentence as MBP in open-access papers (continued):
Sharing a sentence is not in itself a finding about the gene and the disease.
systemic lupus erythematosus (15 papers, 2009 to 2024). An autoimmune multi-organ disease typically associated with vasculopathy and autoantibody production. "Citrullination of MBP in the CNS is correlated with the onset of MS, and it causes other autoimmune diseases, such as systemic lupus erythematosus (SLE) and autoimmune encephalomyelitis." (PMID 34638916, 2021). "Similar to systemic lupus erythematosus (SLE), the blood of MS patients contains abzymes hydrolyzing DNAs and RNAs, myelin basic protein (MBP), histones, and oligosaccharides." (PMID 36901861, 2023).
glioma (13 papers, 2013 to 2025). A benign or malignant brain and spinal cord tumor that arises from glial cells (astrocytes, oligodendrocytes, ependymal cells). "Conversely, the amount of MBP and neurofilaments was lower in high-grade gliomas than in low-grade gliomas in IF staining." (PMID 36713547, 2022). "The density of the streak-like pattern in CLE images was strongly correlated with the amount of MBP and neurofilament in the normal brain and gliomas, and there was a reverse correlation between glioma grade and the quantity of these myelin fibers." (PMID 36713547, 2022). "Comet assays also illustrated that BIP-MPC-NP enhanced the DNA damage induced by TMZ compared with EBP-MPC-NP or MBP-MPC-NP in TMZ-resistant glioma cells." (PMID 32001707, 2020). "Meanwhile, the expressions of myelin-associated proteins (MBP, MOG, MAG and CNP) were unanimously reduced in gliomas." (PMID 30034322, 2018). "Western blot results further confirmed that QUE significantly up-regulated MBP expression, but down-regulated vimentin (a marker for glioma) and GFAP expression." (PMID 28415586, 2017). "In addition, by performing K-M curve analysis, the expression of H19, HOTAIR, miR-148a-3p, miR-222-3p, MBP and HMGA2 had a significant association with glioma patients’ survival." (PMID 40351420, 2025). "This transcription factor has a recognized oncogenic role in glioma growth 64, however in MVNT OLIG2 expression is noted in the context of overall reduced myelination and labelling of VC for myelin basic protein." (PMID 28833756, 2018). "In IDH-mutant/PM gliomas, coordinated hypermethylation in the transcription start site (TSS)/CpG island regions was observed in MO marker (GALC/O1), myelin components (MAG, MBP, MOBP, MOG), and essential regulators of the myelination program (MYRF/C11orf9 and SOX10)." (PMID 37055795, 2023). "The MO marker GALC/O1 and myelin components (e.g., MBP, MOG) were under-expressed in PM gliomas." (PMID 37055795, 2023). "Cells from glioma spheres were grown in serum-containing medium to induce differentiation before they were stained for specific markers for astrocytes (GFAP), oligodendrocytes (MBP) and neurons (βIII-tubulin)." (PMID 24819299, 2014). "Another distinctive feature of the OG cells is their lack of differentiation into astrocytes or mature MBP-positive oligodendrocytes, as would be expected of OPCs, a proposed glioma cell of origin." (PMID 24278309, 2013). "In GSLCs and glioma tissues, Sohlh1 expression was negatively correlated with the expression of GSLC markers, such as Nestin, CD133, CD44, SOX2 and OCT4, whereas Sohlh1 expression was positively correlated with the expression of GSLC differentiation markers, such as MAP2, GFAP and MBP." (PMID 40418209, 2025). "With nanoinhibitors as treatments on TMZ-resistant glioma cells, BIP-MPC-NP simultaneously attenuated p-EGFR and p-MET in cells with EGF and HGF incubation or without EGF and HGF incubation, and this attenuation was more significant than that of EBP-MPC-NP or MBP-MPC-NP group." (PMID 32001707, 2020).
Parkinson disease (11 papers, 2009 to 2025). A progressive degenerative disorder of the central nervous system characterized by loss of dopamine producing neurons in the substantia nigra and the presence of Lewy bodies in the substantia nigra and locus coeruleus. "CSF levels of parkinsonism-associated deglycase, tau, myelin basic protein (MBP), and neurofilament light chain (NfL), which reflect neurodegeneration in the brain, were significantly higher in patients with MSA than in those with Parkinson’s disease." (PMID 41439986, 2025). "AßP-42, tau protein, α-synuclein, asialoganglioside GM1, GFAP, rab-5, ATP-synthase, MBP, and their antibodies have been linked with neurodegeneration and diseases such as AD, Parkinson's disease (PD), and multiple sclerosis (MS)." (PMID 30034864, 2018). "A high dose of FSK (45 mg/kg) raises, recovers and controls the level of MBP in rats suffering from 6-OHDA-induced Parkinsonism." (PMID 36432051, 2022). "The quantitative analysis by the nano-LC-MS method focused on 95 different Parkinson’s disease-relevant proteins (for example, the myelin basic protein, thiosulfate sulfur transferase, and PARK7); among those, only one, PARK7, presented significantly different levels due to treatment." (PMID 33429934, 2021).
diabetes (10 papers, 2012 to 2023). "The levels of NSE and MBP in the mild diabetes group were significantly higher compared with those in the control group (P<0.05)." (PMID 25371752, 2014). "Similar to the present results, diabetes also decreased the expression level of MBP in the brain." (PMID 37892401, 2023). "In addition, the NSE concentration was significantly higher in the severe diabetes group when compared with the mild diabetes group (P<0.05), while the levels of S100B, MBP and ET-1 exhibited a highly statistically significant difference when comparing the two groups (P<0.01)." (PMID 25371752, 2014). "In the severe diabetes group, the levels of S100B, NSE, MBP and ET-1 were all significantly higher compared with those in the control group (P<0.01)." (PMID 25371752, 2014).
epilepsy (10 papers, 2007 to 2023). A brain disorder characterized by episodes of abnormally increased neuronal discharge resulting in transient episodes of sensory or motor neurological dysfunction, or psychic dysfunction. "MBP has a key role in both myelin formation and its stabilization; however, studies that discuss the link between MBP and epilepsy are scarce." (PMID 36980356, 2023). "Similar results reported in animal models of epilepsy also showed increased expression of MBP in the hippocampus, indicating a breakdown in the BBB." (PMID 30274397, 2018). "We did not think it likely that myelin studies would be of relevance in epilepsy in the context of this paper, but additional histopathological analyses, such as LFB for myelin or myelin basic protein, may lead to further useful data in future studies." (PMID 17555988, 2007).
Hydrocephalus (10 papers, 2006 to 2025). Hydrocephalus is an active distension of the ventricular system of the brain resulting from inadequate passage of CSF from its point of production within the cerebral ventricles to its point of absorption into the systemic circulation. "Considering that increasing Neu5Ac upregulates many myelination‐responsive genes, including MBP,30, 31 the effect of Neu5Ac on the rescue of hydrocephalus‐induced demyelination and related neurological deficits needs to be explored." (PMID 37222223, 2023). "Consistent with the results of MBP staining, hydrocephalus induced a profound decrease in the intensity of LFB staining (p < 0.001) in the CC and EC regions, representing a marked demyelination." (PMID 37222223, 2023). "In other cases, GEAP protein (glial fibrillary acidic protein), vimentin, MBP (myelin basic protein), and CNPase are playing a potential role in developing hydrocephaly." (PMID 31662948, 2019). "Raised MBP in post-haemorrhagic and spina bifida with hydrocephalus indicates damage to oligodendrocytes and myelin." (PMID 24351234, 2013). "GFAP was significantly raised only in CSF from post-haemorrhagic hydrocephalus while MBP was significantly raised in post-haemorrhagic and in spina bifida with hydrocephalus infants." (PMID 24351234, 2013). "It is known that in hydrocephalus there is demyelination of the periventricular white matter and so MBP appears as an attractive marker to study the degree of this pathological process." (PMID 17020616, 2006). "MBP can also be present after CNS trauma and hydrocephalus in children and indicate CNS damage." (PMID 40310164, 2025). "Hydrocephalus in Rsph9−/− mice also attenuated the expression of myelin basic protein (MBP), which is a marker of myelinating glia, but it enhanced the expression of oligodendrocyte transcription factor 2 (OLIG2), which is a marker of oligodendrocyte progenitor cells and mature oligodendrocytes." (PMID 32709945, 2020). "The beneficial effect of CEGI can be possibly attributed to the upregulation of MAP-2 and MBP expression, which could ameliorate myelin sheath and axon damage, and to the reduction of the lateral ventricular enlargement and prevention of hydrocephalus secondary to IVH/ICH." (PMID 27782218, 2016). "In their study of 17 patients with hydrocephalus who underwent surgical CSF diversion they observed that the levels of MBP decreased following the shunt operation, suggesting that MBP is an index of brain damage and its levels could be used as an indication for shunting." (PMID 17020616, 2006). "Hydrocephalus led to extensive demyelination in the PVM, presenting as a reduction in MBP fluorescence intensities in the corpus callosum (CC), cingulum bundle (CG), and external capsule (EC, p < 0.01)." (PMID 37222223, 2023). "Although the corpus callosum was thinned, overall the cerebral MBP content (relative to total protein) was not reduced as a consequence of hydrocephalus suggesting that surviving axons remained myelinated." (PMID 25324960, 2014). "The fact that MBP is not detected in FOH and LOH again indicates a lack of direct pathology in these specific aetiologies of hydrocephalus and the possibility to prevent loss of myelination through early intervention." (PMID 24351234, 2013).
cognitive decline (9 papers, 2014 to 2024). "The results demonstrated that WMI was positively associated with cognitive decline (black‐gold: R = 0.638, p < 0.05; MBP: R = 0.655, p < 0.05; MAG: R = 0.673, p < 0.05; n = 10), indicating the occurrence of WMI‐mediated cognitive dysfunction." (PMID 36529961, 2023). "Indeed, white matter changes are an early feature of human AD, and the premature loss of MBP immunostaining observed in our study is consistent with myelin loss being an early event in AD pathology and cognitive decline." (PMID 32619874, 2020). "MBP accounts for approximately one-third of myelin protein, and demyelination in the setting of vitamin B12 deficiency may explain many of the neurologic findings, including the association with cognitive decline." (PMID 29867734, 2018).
encephalitis (9 papers, 2019 to 2025). An acute inflammatory process affecting the brain parenchyma. "MBP autoantibody-associated encephalitis could be an unrecognized form of canine autoimmune encephalopathy and could enable a distinction between lymphatic CNS neoplasia and lymphocytic pleocytosis due to inflammatory disease." (PMID 39403212, 2024). "MBP-specific CD8+ T cells have also been argued to exacerbate brain inflammation through an autoimmune-encephalitis-like effect that promotes the formation of intracerebral and intracerebellar lesions." (PMID 39201672, 2024). "Lumbar puncture (LP) studies including meningitis/encephalitis pathogen panel, venereal disease research laboratory (VDRL), myelin basic protein, anti-GQ1b antibody, and bacterial cultures were initially unremarkable." (PMID 39712688, 2024). "Lumbar puncture studies including a meningitis/encephalitis pathogen panel, venereal disease research laboratory (VDRL), myelin basic protein, anti-GQ1b antibody, and bacterial cultures were initially unremarkable." (PMID 39712688, 2024). "While the presence of myelin basic protein (MBP) in the cerebrospinal fluid (CSF) suggests autoimmune-mediated encephalitis, oligodendrocytes viability and neurons myelination have not been explored yet." (PMID 31684034, 2019). "Likewise, the ability of low doses of SEA to induce encephalitis when co-injected with MBP in mice previously immunized with MBP and showing no sign of disease may share a similar mechanism." (PMID 39727963, 2024).
glaucoma (9 papers, 2020 to 2025). Increased pressure in the eyeball due to obstruction of the outflow of aqueous humor. "In this study, we were unable to confirm previously reported glaucoma-associated autoantibodies such as HSPs, γ-enolase and MBP." (PMID 40149693, 2025). "Upon analysing a case of asymmetrical glaucoma, where the left eye was more severely affected, it was found that there was significantly diminished MBP fluorescence intensity than in the opposite eye." (PMID 39191397, 2024). "For example, Olig2 fluorescence intensity was significantly diminished in glaucoma patients, and was positively correlated with MBP intensity." (PMID 39191397, 2024). "Our findings revealed that alongside nerve shrinkage and degeneration of nerve tissue fascicles, there were significantly less myelin proteins, specifically myelin basic protein (MBP), in glaucoma optic nerves." (PMID 39191397, 2024). "Both glaucoma types showed higher levels of myelin basic protein (MBP), and NTG presented lower levels of anti-α-fodrin antibody, when compared with control individuals—which is contrary to the findings of a previous study." (PMID 34439995, 2021). "The global data were used to determine the discriminating power between control and glaucoma subjects, proposing the MBP, anti-SSA, anti-SSB, and anti-α-fodrin IgG/IgA as useful candidate biomarkers for diagnosis and clinical differentiation within groups." (PMID 34439995, 2021). "South Korean scientists and German scientists proved that the serum levels of anti-MBP antibodies were higher in patients with primary open-angle glaucoma (POAG) and normal-tension glaucoma (NTG)." (PMID 34795572, 2021). "In the ROC analyses, serum MBP level was the best biomarker for discriminating between controls and patients with glaucoma, and serum anti-SSB antibody was the best biomarker for discriminating between NTG and HTG." (PMID 33374330, 2020). "The glaucoma group showed a higher serum MBP level and lower serum anti-α-fodrin antibody level than the control group (p < 0.05)." (PMID 33374330, 2020). "In the receiver operating characteristic curve analysis, the area under the curve (AUC) for serum MBP level was 0.917 in discriminating between controls and patients with glaucoma." (PMID 33374330, 2020). "The serum MBP level was higher in the glaucoma group than in the control group (318.12 ± 146.91 pg/mL vs. 61.91 ± 100.02 pg/mL, respectively, p < 0.001, Mann–Whitney U test)." (PMID 33374330, 2020). "The sensitivity and specificity of the MBP level for discriminating between the control group and patients with glaucoma at the optimal cut-off point of 183.4 μg/μL were 85.7% and 88.2%, respectively." (PMID 33374330, 2020). "The high serum MBP level in patients with glaucoma in the present study suggests optic nerve damage or brain damage and can be used as a marker to distinguish between control participants and patients with glaucoma." (PMID 33374330, 2020). "The most effective biomarker for discriminating between control participants and patients with glaucoma was the serum MBP level with the cut off value of 183.4pg/ml, while for discriminating between patients with NTG and HTG it was the serum anti-SSB level with the cut off value of 0.962." (PMID 33374330, 2020). "In this study, the serum level of MBP, a trans-membrane protein that plays an important role in the myelination process in the central and peripheral nervous system, was higher in the patients with glaucoma." (PMID 33374330, 2020). "Serum MBP level can be used as a screening test for glaucoma." (PMID 33374330, 2020). "Therefore, anti-MBP antibodies in serum produced by demyelination may be a marker to distinguish between control participants and patients with glaucoma." (PMID 34795572, 2021). "Serum MBP levels may help to detect glaucoma and cannot be used to determine the glaucoma severity." (PMID 33374330, 2020).
glaucoma (continued). "For glaucoma, PTGDS, GSTP1, SPD1, and CST3 were expressed significantly higher in almost all tissues; CRP, ALB, and TTR were markedly increased in the liver; MBP and TF exhibited high expression in the brain." (PMID 37052519, 2023).
injury (9 papers, 2014 to 2025). Damage inflicted on the body as the direct or indirect result of an external force, with or without disruption of structural continuity. "MBP has been associated with neuronal death and trauma and has been found to be increased in CSF of dogs post traumatic brain injury." (PMID 38802853, 2024). "Following a brain injury, MBP is liberated from the plasma membrane and enters the extracellular matrix." (PMID 39522688, 2025). "Brain injury also damages the blood-brain barrier or alters its permeability, resulting in a significant increase in serum MBP and BDNF concentrations." (PMID 37645013, 2023). "As a result, we were able to document that elevated levels of MBP and NF-H in the CSF should be considered as useful neuroinjury biomarkers of traumatic brain injury." (PMID 33895854, 2021). "Our findings suggest the possibility that MBP and BDNF work in concert to protect against or enhance recovery from brain injury, mediating the risk of long-term mechanical and psychological injury." (PMID 26251769, 2015). "In a series of prior works, we have established that demyelination contributes to neuropathic pain in part through T cell-mediated autoreactivity of MBP fragments, such as MBP84-104, proteolytically released after a focal nerve trauma." (PMID 38590761, 2024).
asthma (8 papers, 2018 to 2024). "Epithelial cells in chronic asthma patients are damaged by granular products derived from eosinophils, such as MBP (major basic protein), and this increases the susceptibility to rhinovirus (RV) infection, which is one of the most frequent causes of asthma exacerbation." (PMID 36615179, 2023). "In the comparison between the PM/OVA and PM groups, OVA affected both the immediate and late reaction of asthma by upregulation of the interleukin-4 (IL-4), FcεRI, eotaxin, and MBP in asthma pathway, and cytokine-cytokine receptor interaction pathway (respectively)." (PMID 36934237, 2023). "For in vivo detection, the enzyme-linked immunosorbent assay (ELISA) method was used to detect the release of the MBP and EDN from eosinophils in a children asthma model." (PMID 35055294, 2022). "The BLAST analysis showed that MBP and WNK2 DEGs have five other similar genes in the asthma-related gene group." (PMID 32512817, 2020). "Studies on EOXs role in the pathology of asthma have revealed that the composition of EOXs in patients with asthma and healthy individuals are similar in size and carries important enzymes such as EPO (Eosinophil peroxidase), MBP (Major basic protein), and ECP (Eosinophil cationic protein)." (PMID 35550636, 2022).